VIPAS39 (VPS33B interacting protein, apical-basolateral polarity regulator, spe-39 homolog)
Description:
Proposed to be involved in endosomal maturation implicating in part VPS33B. In epithelial cells, the VPS33B:VIPAS39 complex may play a role in the apical RAB11A-dependent recycling pathway and in the maintenance of the apical-basolateral polarity. May play a role in lysosomal trafficking, probably via association with the core HOPS complex in a discrete population of endosomes; the functions seems to be independent of VPS33B. May play a role in vesicular trafficking during spermatogenesis (By similarity). May be involved in direct or indirect transcriptional regulation of E-cadherin (By similarity).
Synonyms: hSPE-39; C14orf133; SPE39; VIPAR; VPS16B; SPE-39
Tractability: PROTAC: ubiquitination databases record sites on it; its protein half-life has been measured.
Gene: Protein-coding gene on chromosome 14 (77,426,675 to 77,457,952, reverse strand). Ensembl gene ENSG00000151445.
Subcellular location: Cytoplasm; Cytoplasmic vesicle; Early endosome; Recycling endosome; Late endosome
Gene Ontology:
Molecular function: protein binding; protein-containing complex binding
Biological process: autophagosome maturation; collagen metabolic process; endosome to lysosome transport; intracellular protein transport; peptidyl-lysine hydroxylation; phagosome-lysosome fusion; vacuolar transport
Cellular component: cytoplasm; early endosome; endosome; Golgi apparatus; HOPS complex; late endosome; recycling endosome; vesicle tethering complex; cytoplasmic vesicle
Genetic constraint (gnomAD): Loss-of-function variants: 63 observed, 89.32 expected, observed/expected ratio (o/e) 0.71, 90% interval 0.57 to 0.87. The upper end of that interval is the gene's LOEUF score, 0.87, which puts it in group 3 of 6, group 1 being the genes least tolerant of losing a copy. Missense variants: 499 observed, 636.74 expected, observed/expected ratio (o/e) 0.78, 90% interval 0.73 to 0.84. Synonymous variants: 192 observed, 229.23 expected, observed/expected ratio (o/e) 0.84, 90% interval 0.74 to 0.94.
Gene-disease validity (ClinGen):
ClinGen rates the evidence that VIPAS39 causes each of these diseases.
arthrogryposis, renal dysfunction, and cholestasis 2 (autosomal recessive): Definitive.
Homologues: Orthologues: chimpanzee VIPAS39 (100% identical), macaque VIPAS39 (99% identical), guinea pig VIPAS39 (96% identical), rabbit VIPAS39 (96% identical), mouse Vipas39 (95% identical), dog VIPAS39 (93% identical), pig VIPAS39 (92% identical), rat Vipas39 (92% identical), tropical clawed frog vipas39 (71% identical), zebrafish vipas39 (64% identical), Drosophila melanogaster Vps16B (26% identical), Caenorhabditis elegans spe-39 (23% identical).
Diseases named in the same sentence as VIPAS39 in open-access papers:
VIPAS39 is named in the same sentence as 10 diseases in open-access papers, as found by Europe PMC text mining. Sharing a sentence is not in itself a finding about the gene and the disease. The quoted sentences say what the papers report.
arthrogryposis (7 papers, 2015 to 2025). A rare, non-progressive congenital disorder characterized by multiple joint contractures which are present at birth. "Patients with mutations in the genes VPS33B and VIPAS39 have been reported with Arthrogryposis, Renal dysfunction and Cholestasis (ARC) syndrome (OMIM #208085 and #613404)." (PMID 29409756, 2018). "Mutations in VPS33B and VIPAS39 cause the severe multisystem disorder Arthrogryposis, Renal dysfunction and Cholestasis (ARC) syndrome." (PMID 29409756, 2018). "VPS33B forms a protein complex with VIPAS39 (VIPAR), and mutations in the VPS33B gene cause arthrogryposis-renal dysfunction-cholestasis syndrome." (PMID 39812558, 2025). "Arthrogryposis, renal dysfunction, and cholestasis syndrome (ARCS) is a rare autosomal recessive disorder caused by mutations in VPS33B (ARCS1) and VIPAS39 (ARCS2)." (PMID 35151346, 2022). "VPS33B forms a complex with VIPAR (also known as SPE-39, VIPAS39 or VPS16B), and mutations in either of these proteins can cause arthrogryposis, renal dysfunction, and cholestasis (ARC) syndrome." (PMID 29778605, 2018). "The discovery that mutations in VPS33B or VPS16B (VIPAS39, VIPAR, SPE-39) are responsible for arthrogryposis, renal dysfunction, and cholestasis (ARC) syndrome provided the first evidence that the biogenesis of α-granules depends on membrane trafficking machinery." (PMID 40309239, 2025). "Indeed, VIPAS39 and VPS33B deficiencies, which cause arthrogryposis, renal dysfunction and cholestasis syndrome (ARC), result in a reduction of LH3-dependent post-translational modification of COLLIV in inner medullary collecting duct cells accompanied by an abnormal ECM deposition." (PMID 30716086, 2019).
cholestasis (4 papers, 2013 to 2025). Impairment of the bile flow caused by obstruction within the liver, or outside the liver in the bile duct system. "Thus, we raised awareness of the mild clinical picture of ARCS, and we propose that molecular analysis of the VPS33B and VIPAS39 should be considered in patients with normal GGT cholestasis, and not only for patients with the complete ARCS phenotype." (PMID 35281816, 2022). "Consequently, we believe that the molecular analysis of the VPS33B and VIPAS39 should be considered in patients with normal gamma-glutamyl transferase cholestasis." (PMID 35281816, 2022).
(ARC) syndrome (3 papers, 2014 to 2021). "VPS33B or VIPAS39 variants (respectively) were identified in patients with a rare multisystem disorder called arthrogryposis-renal dysfunction-cholestasis (ARC) syndrome." (PMID 33557414, 2021).
VIPAS39 also shares sentences with these, for which no sentence is quoted: renal dysfunction (3 papers); ichthyosis (2); arthrogryposis-renal dysfunction-cholestasis syndrome (1); bacterial infection (1); cyst (1); lymphedema (1); renal tubular dysfunction (1).